MIR215 (microRNA 215)
Synonyms: hsa-mir-215; MIRN215; miRNA215; mir-215
Gene: MicroRNA gene on chromosome 1 (220,117,853 to 220,117,962, reverse strand). Ensembl gene ENSG00000207590.
Gene Ontology:
Biological process: miRNA-mediated post-transcriptional gene silencing
Cellular component: RISC complex
Diseases named in the same sentence as MIR215 in open-access papers:
MIR215 is named in the same sentence as 2 diseases in open-access papers, as found by Europe PMC text mining. Sharing a sentence is not in itself a finding about the gene and the disease. The quoted sentences say what the papers report.
gastric cancer (1 paper, 2025). A primary or metastatic malignant neoplasm involving the stomach. "Studies have shown that MIR215 can promote the proliferation, migration, and invasion of gastric cancer cells." (PMID 40176817, 2025).
MIR215 also shares sentences with these, for which no sentence is quoted: tumor (1 paper).